NPC1L1 (NPC1 like intracellular cholesterol transporter 1)
Diseases named in the same sentence as NPC1L1 in open-access papers (continued):
Sharing a sentence is not in itself a finding about the gene and the disease.
hyperlipidemia (13 papers, 2014 to 2025). "In both the GLGC2013 and ieu-b-4846, the therapeutic effect of NPC1L1 inhibitors was observed solely for hyperlipidemia (P < 0.05/782)." (PMID 40596422, 2025). "In all three datasets, NPC1L1 inhibitors consistently demonstrated an inhibitory effect on hyperlipidemia." (PMID 40596422, 2025). "Our findings show that laminarin can counteract diet-induced hyperlipidemia by reducing intestinal cholesterol uptake, possibly through the down-regulation of NPC1L1 expression, a key transporter for cholesterol uptake." (PMID 38132943, 2023). "Postprandial hyperlipidemia was attenuated by pemafibrate via inhibition of intestinal cholesterol transporter NPC1L1 mRNA expression in small intestinal mucosa in mice fed a high-fat diet." (PMID 37233667, 2023). "In contrast, the NPC1L1 inhibitor ezetimibe is currently registered for treating hyperlipidemia in the clinic, and possesses potential for drug repurposing in oncology therapeutic areas." (PMID 35023619, 2022). "Pemafibrate suppressed postprandial hyperlipidemia by inhibiting the mRNA expression of intestinal cholesterol transporter NPC1L1 in small intestine mucosa in mice fed a high-fat diet [60•, 61]." (PMID 31974794, 2020). "Attenuation of postprandial hyperlipidemia may result from suppression of chylomicron synthesis and secretion by inhibiting NPC1L1-mediated cholesterol absorption as well as PPARα activation in the small intestines." (PMID 37233667, 2023). "Increased expression of NPC1L1 and MTP is highly associated with postprandial hyperlipidemia." (PMID 37762244, 2023). "lactis could improve hyperlipidemia by regulating bile acid metabolism through downregulating FXR genes while reducing exogenous cholesterol absorption through modulating the NPC1L1 gene." (PMID 37022264, 2023). "Thus, pemafibrate attenuates postprandial hyperlipidemia by suppression of chylomicron synthesis and secretion via inhibition of cholesterol absorption via NPC1L1 as well as PPARα activation in the small intestines." (PMID 31974794, 2020). "And in patients with hyperlipidemia treated with cholesterol synthesis by HMGCR inhibitor Atorvastatin, the level of NPC1L1 gene expression was significantly increased." (PMID 34867343, 2021). "However, PMs have sound effects on promoting cholesterol excretion and inhibiting NPC1L1 expression, but the impact of reducing HFD-induced hyperlipidemia in the body is not as good as CO drugs." (PMID 35745830, 2022).
diabetes (11 papers, 2012 to 2024). "In contrast, a large genetic study that assessed life-long exposure to lower LDL-C levels due to carriage of genetic variants of NPC1L1, the target of ezetimibe, showed an increased risk of diabetes and suggested that on glucose homeostasis may be a class effect of LDL-C lowering agents." (PMID 39501240, 2024). "Our previous study showed that HMGCR and NPC1L1 gene polymorphisms were associated with the susceptibility of PTVD and the risk of diabetes in PTVD." (PMID 37355634, 2023). "LDL‐C lowering was associated with higher HbA1c, an indicator for increased risk of diabetes, for both HMGCR (beta in mmol/mol per 1 mg/dL decrease in LDL‐C 0.03, 95% CI 0.01, 0.04) and NPC1L1 (beta 0.05, 95% CI 0.03, 0.08)." (PMID 37208559, 2023). "In patients with diabetes, expression of NPC1L1 is enhanced, whereas there is reduced expression of ATP-binding cassette transporters (ABC) G5 and G8, which are involved in returning cholesterol from small intestinal epithelial cells to the small bowel lumen." (PMID 24053480, 2013). "We demonstrated in animal models of diabetes that NPC1L1 was upregulated and in diabetic patients, and we demonstrated an increase in NPC1L1 mRNA suggesting a mechanism for an increase in cholesterol absorption." (PMID 22007304, 2012). "A large-scale meta-analysis of genetic association studies has shown that exposure to LDL-C-lowering genetic variants near NPC1L1 and PCSK9 genes is associated with an increased risk of type 2 diabetes, with a 1.19 to 2.42-fold increase in overall diabetes risk per 1 mmol/L decrease in LDL-C." (PMID 39717102, 2024). "In the Psammomys obesus animal model of type 2 diabetes the ABC G5 /8 reduction was associated with a reduction rather than increase in cholesterol absorption perhaps due to a reduction in NPC1L1 which the authors found, suggesting a difference between different animal models of diabetes." (PMID 22007304, 2012). "Phytosterol composition, the characteristics of its food matrix, clinical conditions that affect cholesterol metabolism such as type 2 diabetes mellitus (DM2), and single-nucleotide polymorphisms (SNPs) in NPC1L1 and apolipoprotein E (ApoE) may modify both their bioavailability and their efficacy." (PMID 35406067, 2022). "The major abnormality of lipoprotein metabolism in diabetes is related to TG-rich lipoproteins, and various steps in the synthesis of CMs and VLDL particles seem to be abnormal, including upregulation of the expression of NPC1-L1, intestinal MTP and intestinal ACAT." (PMID 25110536, 2014).
Obesity (11 papers, 2013 to 2025). Accumulation of substantial excess body fat. "NPC1L1 deficiency protects mice against obesity induced by various HFDs that are low in cholesterol." (PMID 34943976, 2021). "In the liver of these Hupki mice, expression of Tnfα and Npc1l1 genes is higher in R72 than P72 mice, where they induce inflammation and increase cholesterol absorption, respectively, predisposing R72 animals to obesity and insulin resistance." (PMID 30651598, 2019). "We and others have shown that NPC1L1 inhibition or deletion protects mice against HFD-induced obesity." (PMID 34943976, 2021). "Interestingly, NPC1L1 is not only a relevant molecular target for hyperlipidemia therapy but also for obesity management, considering that the cholesterol uptake rate is known to be one of the main elevating factors of obesity." (PMID 37958912, 2023). "Genetic deletion of NPC1L1 protects mice against HFD-induced obesity." (PMID 34943976, 2021). "Genetic deletion of NPC1L1 or ezetimibe treatment protects mice from high-fat diet (HFD)-induced obesity; however, the molecular mechanisms responsible for this therapeutic benefit remain unknown." (PMID 34943976, 2021). "While the association of Sortilin to cardiovascular disease is established, whether Sortilin plays a role in adipose tissue function, body weight gain, and factors shared by both cardiovascular disease and obesity, like NPC1L1, is unclear." (PMID 29899496, 2018). "Therefore, MGEL20154, also a potent activator of pparα, could inhibit NPC1L1 expression in Caco-2 cells, suggesting that it can suppress cholesterol absorption into cells from the digestive tract and result in an anti-obesity effect." (PMID 36864459, 2023). "It is currently unknown how NPC1L1 modulates diet-induced obesity." (PMID 34943976, 2021). "Lack of NPC1l1 has an effect on cholesterol metabolism, and inhibition and lack of NPC1L1 has been shown to protect mice from obesity induced by the HFD." (PMID 38721604, 2024). "In the liver biopsies from men with and without obesity, the mean RPKM values for NPC1L1 amounted to 11 ± 0.68 and 13 ± 1.1 (p = 0.45)." (PMID 40004948, 2025).
type 2 diabetes (11 papers, 2009 to 2025). "NPC1L1 protein expression, a direct target of ezetimibe, was enhanced by hyperglycemia in cultured intestinal cells and mRNA expression of NPC1L1 was also increased in type 2 diabetes patients." (PMID 30093717, 2018). "In another study, type 2 diabetics expressed higher levels of NPC1L1 and MTP mRNA than control subjects." (PMID 28646901, 2017). "In the present dataset, the mRNA expression levels of NPC1L1, c7orf50, and GPR146, respectively, were similar in the individuals with type 2 diabetes compared with the age-, sex-, and BMI-matched healthy individuals." (PMID 40004948, 2025). "We report robust expression of NPC1L1 in the small intestines and negligible expression in the large intestines of individuals with and without type 2 diabetes." (PMID 40004948, 2025).
gallstones (10 papers, 2010 to 2025). Solid crystalline precipitates in the biliary tract, usually formed in the gallbladder, resulting in the condition of cholelithiasis. "It is important to understand the link between the sterol transporters ABCG5/8 and NPC1L1 and intestinal cholesterol absorption as well as de novo synthesis in gallstone patients stratified according to 19H risk allele." (PMID 23406058, 2013). "Since various Niemann-Pick C1-like 1 (NPC1L1) mutations have been found to increase biliary cholesterol concentrations, which in turn increases the risk of gallstone, the abundance of NPC1L1 proteins in the human liver is considered a plausible defense against gallstone." (PMID 40463747, 2025). "Our study suggests that the G allele of the NPC1L1 polymorphism g1679C>G may be a positive marker of gallstone formation risk." (PMID 26800364, 2016). "Ezetimibe, a selective NPC1L1 inhibitor, prevents gallstone formation in mice, indicates that NPC1L1 is a valid therapeutic target against the CGD." (PMID 31829191, 2019). "Previous studies demonstrated that inhibition of intestinal NPC1L1 prevents gallstone formation; in addition, ezetimibe, a selective NPC1L1 inhibitor, prevents gallstone formation in mice, indicating that NPC1L1 is a valid therapeutic target against CGD." (PMID 30105244, 2018). "In this study, we genotyped NPC1L1 SNPs in patients from two cohorts consisted of gallstone disease and their healthy counterparts, and compared NPC1L1 expression in liver biopsies from gallstone patients as well." (PMID 26800364, 2016). "In summary, our present study demonstrated that curcumin can prevent formation of gallstones, and it is likely due to reduced expression of NPC1L1 that regulated by SREBP2." (PMID 26335572, 2015). "A decreased hepatic NPC1L1 down-regulation in normal weight female gallstone carriers was already described by Cui." (PMID 23406058, 2013). "Recently, a Chinese study demonstrated an increased intestinal expression of NPC1L1 in gallstone patients as a mechanism for upregulated cholesterol absorption in the small intestine." (PMID 23406058, 2013). "Second, the ileal expression of the sterol transporters ABGG5, ABCG8 and NPC1L1 as well as of their relevant transcription factors is similar between gallstone carriers and controls." (PMID 23406058, 2013). "Thus, the effect of EZE on CGD still requires further clinical trials, although the potential side effect of EZE on hepatic NPC1L1 during gallstone formation was excluded in this study." (PMID 36209166, 2022). "Moreover, another cohort study showed increased expression of NPC1L1 in the jejunal mucosa from Chinese gallstone patients." (PMID 26800364, 2016). "Because of the suggested role of NPC1L1 in uptaking biliary cholesterol into hepatocytes in human, there are concerns that ezetimibe treatment might induce gallstone formation through inhibition of hepatic NPC1L1." (PMID 26800364, 2016). "What is more, the decreased hepatic NPC1L1 levels may leads to the cholesterol supersaturation because of the malabsorption of biliary cholesterol in the liver in Chinese female gallstone patients." (PMID 25107305, 2014). "In conclusion, in our study of normolipidemic, nonobese Chinese female gallstone patients, the supersaturation of the bile with cholesterol was associated with a decreased expression of hepatic NPC1L1, which was possibly mediated by hepatic SREBP2." (PMID 20144195, 2010). "One animal model study also found ezetimibe caused dose-dependent reductions in biliary cholesterol levels, and prevented gallstone formation; however, mice’s lack of hepatic NPC1L1 should be take into consideration." (PMID 37888101, 2023). "Notably, ABCG5/8 and NPC1L1 expression was similar in gallstone carriers and controls regardless of p.D19H presence." (PMID 23406058, 2013). "However, further studies are required to elucidate why decreased NPC1L1 expression occurred in female patients with gallstones, but not male gallstone patients (data not show)." (PMID 20144195, 2010).
gallstones (continued). "In addition, LXRβ and PPARδ coordinate Niemann-Pick C1-like L1(NPC1L1/ABCA1)-dependent vectorial cholesterol flux from bile through cholangiocytes and manipulation of these processes may influence bile composition in murine with gallstone." (PMID 25107305, 2014).
hepatocellular carcinoma (10 papers, 2013 to 2025). A malignant tumor that arises from hepatocytes. "In the SMR analysis, it was observed that HMGCR expression decreased the risk of hepatocellular carcinoma (OR = 0.11, 95% CI: 0.02–0.68, p = 0.02), while NPC1L1 expression increased the risk of gastric cancer (OR = 1.33, 95% CI: 1.08–1.64, p < 0.01)." (PMID 40443776, 2025). "Our study results suggested a potential risk association between HMGCR inhibitors and NPC1L1 with hepatocellular carcinoma and gastric cancer." (PMID 40443776, 2025). "NPC1L1 is a crucial protein for intestinal cholesterol absorption and is closely associated with cancer, influencing the development of various types of cancer, including colorectal cancer, head and neck squamous cell carcinoma, ovarian cancer, and hepatocellular carcinoma." (PMID 40430847, 2025). "This suggests that HMGCR and NPC1L1 are promising drug targets for treating hepatocellular carcinoma and GC, and the current results are less likely to be influenced by pleiotropy." (PMID 40443776, 2025). "NPC1L1‐mediated LDL was positively associated with rectal cancer (OR = 4.22, 95% CI: 1.21–14.73, p = 0.02) and hepatocellular carcinoma (OR = 82.99, 95% CI: 1.70–4062.70, p = 0.03)." (PMID 40443776, 2025). "In rat hepatoma cell lines, ezetimibe appears to work by either preventing the interaction between NPC1L1 and cholesterol or by blocking the tunnel of NPC1L1, thereby reducing cholesterol transport." (PMID 41451371, 2025). "The findings suggest an increased risk of hepatocellular carcinoma with HMGCR inhibitors, while NPC1L1 inhibitors are associated with a reduced risk of gastric cancer." (PMID 40443776, 2025). "For example, NPC1L1 expression is downregulated in hepatocellular carcinoma but upregulated in pancreatic and colon cancers." (PMID 39598242, 2024). "Studies on hepatoma cells have revealed that NPC1L1 is predominantly localized to intracellular components but relocated to the plasma membrane when acute cholesterol depletion via MβCD occurred." (PMID 22740150, 2013). "In fact, the physiological relevance of NPC1L1receptor has been directly connected to an enhanced cholesterol uptake during Dengue virus infection, and the drug ezetimibe inhibits Dengue virus infection in the human hepatoma cell line (Huh-7) by blocking NPC1L1." (PMID 38672177, 2024). "The MR analysis indicated a negative association between HMGCR‐mediated LDL and hepatocellular carcinoma (OR = 0.06, 95% CI: 0.00–0.81, p = 0.03), and a positive association between NPC1L1‐mediated LDL and gastric cancer risk (OR = 15.45, 95% CI: 5.96–40.56, p < 0.01)." (PMID 40443776, 2025). "The expression of NPC1L1 is known to vary, with lower levels reported in hepatocellular carcinoma (HCC) but higher levels in pancreatic and colon cancers." (PMID 39598242, 2024). "Although the role of NPC1L1 in intestinal cholesterol absorption has been well established, most mechanistic studies were performed in rat or human hepatoma cells in vitro, and it remains controversial whether NPC1L1-mediated cholesterol absorption is a vesicular endocytic process." (PMID 39872735, 2023). "NPC1L1 expression was found to be downregulated in hepatocellular carcinoma (HCC) but upregulated in pancreatic cancer." (PMID 34511128, 2021). "In contrast, in hepatocellular carcinoma (HCC), low NPC1L1 expression correlates with a higher incidence of poorly differentiated tumors, vascular invasion, and an increased number of patients with advanced pathological stages." (PMID 39598242, 2024). "It is putatively regarded that NPC1L1 intakes extracellular cholesterol through formation of endocytosis vesicle assembled by clathrin/AP2 complex, which is largely based on in vitro experiments using rat and human hepatoma cells overexpressing NPC1L1-EGFP." (PMID 39872735, 2023).
hepatocellular carcinoma (continued). "For example, NPC1L1 mRNA levels are reduced by addition of cholesterol through sterol regulatory element binding protein 2 (SREBP2) and increased by depletion of cholesterol in human Caco-2 colon cancer cell and Huh7 hepatoma cell lines." (PMID 39872735, 2023).